RAPGEFL1 (Rap guanine nucleotide exchange factor like 1)
Description:
Probable guanine nucleotide exchange factor (GEF).
Synonyms: Link-GEFII
Tractability: Antibody: its Gene Ontology location is reachable by antibodies, with medium confidence. PROTAC: ubiquitination databases record sites on it; its protein half-life has been measured.
Gene: Protein-coding gene on chromosome 17 (40,177,010 to 40,195,656, forward strand). Ensembl gene ENSG00000108352.
Subcellular location (Human Protein Atlas): Microtubules; Nucleoplasm; Cytokinetic bridge
Gene Ontology:
Molecular function: guanyl-nucleotide exchange factor activity
Biological process: G protein-coupled receptor signaling pathway; nervous system development; Rap protein signal transduction; small GTPase-mediated signal transduction
Cellular component: membrane; plasma membrane
Genetic constraint (gnomAD): Loss-of-function variants: 28 observed, 55.14 expected, observed/expected ratio (o/e) 0.51, 90% interval 0.38 to 0.7. The upper end of that interval is the gene's LOEUF score, 0.7, which puts it in group 2 of 6, group 1 being the genes least tolerant of losing a copy. Missense variants: 489 observed, 594.94 expected, observed/expected ratio (o/e) 0.82, 90% interval 0.76 to 0.89. Synonymous variants: 222 observed, 233.82 expected, observed/expected ratio (o/e) 0.95, 90% interval 0.85 to 1.06.
Homologues: Orthologues: chimpanzee RAPGEFL1 (99% identical), dog RAPGEFL1 (97% identical), pig RAPGEFL1 (97% identical), mouse Rapgefl1 (94% identical), rat Rapgefl1 (94% identical), guinea pig RAPGEFL1 (90% identical), rabbit RAPGEFL1 (88% identical), macaque RAPGEFL1 (88% identical), tropical clawed frog rapgefl1 (62% identical), zebrafish rapgefl1 (49% identical). Paralogues in human: RAPGEF4 (36% identical), RAPGEF5 (33% identical), RAPGEF3 (31% identical), RAPGEF2 (22% identical), RAPGEF6 (19% identical), RAPGEF1 (17% identical), RASGRF1 (14% identical), RASGRF2 (14% identical), RASGEF1B (13% identical), RALGDS (13% identical), RGL3 (13% identical), SOS2 (13% identical), and 12 more.
Diseases named in the same sentence as RAPGEFL1 in open-access papers:
RAPGEFL1 is named in the same sentence as 5 diseases in open-access papers, as found by Europe PMC text mining. Sharing a sentence is not in itself a finding about the gene and the disease. The quoted sentences say what the papers report.
meningioma (1 paper, 2023). A generally slow growing tumor attached to the dura mater. "Here, TRAF7 meningiomas expressed a high number of specific DEGs, including RAPGEFL1, KRT16, KRT6A, IL1RL1, NOS1, and others." (PMID 36937440, 2023).
RAPGEFL1 also shares sentences with these, for which no sentence is quoted: cancer (1 paper); lung adenocarcinoma (1); thyroid cancer (1); tumor (1).